SMAD1 (SMAD family member 1)
Diseases named in the same sentence as SMAD1 in open-access papers (continued):
Sharing a sentence is not in itself a finding about the gene and the disease.
chondrosarcoma (2 papers, 2012 to 2017). A malignant cartilaginous matrix-producing mesenchymal neoplasm arising from the bone and soft tissue. "Nuclear phosphorylated Smad1/5/8 and Smad2 were found in all tumors analyzed and the activity of both signaling pathways was confirmed by functional reporter assays in 2 chondrosarcoma cell lines." (PMID 23088614, 2012). "Immunohistochemical analysis furthermore revealed that phosphorylated Smad1/5/8 and endoglin expression were significantly higher in high-grade compared to low-grade chondrosarcoma and correlated to each other." (PMID 23088614, 2012). "In central chondrosarcoma, we found significantly higher expression of endoglin in high-grade tumors and a correlation of endoglin expression to Smad1/5/8 activity." (PMID 23088614, 2012). "First, p-SMAD3 and p-SMAD1/5 accumulated in nuclei of chondrosarcoma cells, whereas PEG10 was abundantly expressed in enchondroma cells, indicating that expression of PEG10 and activated R-SMADs were mutually exclusive between these benign and malignant cartilage tumours." (PMID 29044189, 2017). "The correlation of Smad1/5/8 activity to endoglin expression suggests that, as described in other cell types, endoglin could enhance Smad1/5/8 signaling in high-grade chondrosarcoma cells." (PMID 23088614, 2012). "The ALK1/ALK5 ratio in chondrosarcoma could thus favor Smad1 activation in comparison to normal cartilage." (PMID 23088614, 2012). "In that case, elevated TGFβ3 expression in grade III chondrosarcoma compared to grade I could contribute to Smad1/5/8 activation in these tumors." (PMID 23088614, 2012). "In order to establish whether the BMP and TGFβ signaling pathways are active in central chondrosarcoma, the presence of nuclear phosphorylated Smad1/5/8 and Smad2 was evaluated by immunohistochemical analysis." (PMID 23088614, 2012). "We have shown that the BMP and TGFβ signaling pathways are active in conventional central chondrosarcoma and that phosphorylated Smad1/5/8 and endoglin expression were significantly higher in high-grade compared to low-grade chondrosarcoma and correlated to each other." (PMID 23088614, 2012). "This correlation suggests that, as described in other cell types, endoglin could enhance Smad1/5/8 signaling in high-grade chondrosarcoma cells." (PMID 23088614, 2012). "In this context, thus, endoglin and Smad1 signaling correlate to undifferentiated states of proliferating chondrogenic precursors, which is in line with higher expression levels in high-grade chondrosarcoma." (PMID 23088614, 2012). "Phosphorylated Smad1/5/8 and Smad2 was detected in all chondrosarcoma samples analyzed." (PMID 23088614, 2012). "Endoglin expression coupled to Smad1/5/8 activation could thus represent a functionally important signaling axis for the progression of chondrosarcoma and a regulator of the undifferentiated phenotype of high-grade tumor cells." (PMID 23088614, 2012). "This correlation suggests that endoglin expression in high-grade chondrosarcoma could represent a determinant of elevated Smad1/5/8 activation in these tumors." (PMID 23088614, 2012). "The dissection of signaling pathways in chondrosarcoma cells would be necessary to determine whether the correlation of endoglin expression to Smad1/5/8 phosphorylation in these cells truly reflects an enhanced activation of this signaling axis in high grade chondrosarcoma." (PMID 23088614, 2012). "As positive controls, SB431542 and LDN193189 inhibitors completely abolished TGF-β1-induced SMAD3 phosphorylation and BMP-6-mediated activation of SMAD1/5/9, respectively, in both SW1353 and Hs 819.T chondrosarcoma cell lines (lanes 4–7 and 11–14)." (PMID 29044189, 2017). "They found strong activation of both SMAD1/5/9 and SMAD2 in chondrosarcomas in a grade-dependent fashion, while a high rate of phosphorylated SMAD2 was associated with shorter metastasis-free survival." (PMID 29044189, 2017).
chondrosarcoma (continued). "We analysed seven enchondromas, and 11 grade 1 and seven grade 2 chondrosarcomas to evaluate the activity of SMAD3 and SMAD1/5." (PMID 29044189, 2017). "Here, we found highly active transforming growth factor-β (TGF-β) and bone morphogenetic protein (BMP) signalling in human chondrosarcomas compared with enchondromas by immunohistochemistry of phosphorylated SMAD3 and SMAD1/5." (PMID 29044189, 2017). "Expression of p-SMAD1/5 showed no statistical difference between enchondroma and grade 1 chondrosarcoma." (PMID 29044189, 2017). "Our reporter assay indicates that the Smad1 and Smad2 signaling pathways may not be relevant for proliferation of chondrosarcoma cells." (PMID 23088614, 2012). "However, in chondrosarcoma no hypertrophic differentiation occurs and we have observed that phosphorylated Smad1/5/8 was elevated in high-grade tumors with a less differentiated phenotype." (PMID 23088614, 2012).
colitis (2 papers, 2012 to 2023). Inflammation of the colon. "TNFα inhibits hepcidin expression in two distinct types of innate colitis, with down-regulation of Smad1 protein playing an important role in this process." (PMID 22675442, 2012). "Expression and activation of Smad1, a positive regulator of hepcidin transcription, were assessed during colitis and following administration or neutralization of TNFα." (PMID 22675442, 2012). "Taken together, our findings suggest that the inhibitory effect of TNFα on hepcidin expression during DSS colitis is mediated by down-regulation of Smad1 protein (and possibly Smad5 and Smad8) and consequent interference with BMP-activated signals." (PMID 22675442, 2012). "The DSS colitis-induced decrease in Smad1 protein expression was prevented by TNFα neutralization." (PMID 22675442, 2012). "We found that hepatic expression of the Smad1 protein, one of the receptor-associated Smads that transduces signals from the BMP receptor complex, was decreased significantly in the mice with DSS colitis." (PMID 22675442, 2012).
diffuse intrinsic pontine glioma (2 papers, 2019 to 2021). A neuroglial tumor that arises from the middle portion of the brain stem. "In addition to the R206H mutation, almost all ACVR1 mutations detected in FOP and diffuse intrinsic pontine glioma (DIPG) also presented enhanced responsiveness to BMP, resulting in higher SMAD1/5/8 signalling upon BMP stimulation." (PMID 31683698, 2019).
embryonal carcinoma (2 papers, 2004 to 2017). A non-seminomatous malignant germ cell tumor characterized by the presence of large germ cells with abundant cytoplasm resembling epithelial cells, geographic necrosis, high mitotic activity, and pseudoglandular and pseudopapillary structures formation. "Our results, obtained in an anamniotic model system, the Xenopus embryo, and in murine embryonic carcinoma cells, indicate that MAB21L2 interacts functionally with SMAD1, a nuclear transducer of BMP2/4/7 signaling." (PMID 15613244, 2004).
endothelial dysfunction (2 papers, 2022 to 2024). In vascular diseases, endothelial dysfunction is a systemic pathological state of the endothelium (the inner lining of blood vessels) and can be broadly defined as an imbalance between vasodilating and vasoconstricting substances produced by (or acting on) the endothelium. "While moderate SMAD1/5 activation is required to maintain endothelial quiescence, excessive SMAD1/5 signaling promotes endothelial dysfunction." (PMID 36171573, 2022). "FK506 (tacrolimus) interacts with FKBP12, activates Smad1/5/8 with or without BMPR2 mutations, recovers endothelial dysfunction, and ameliorates PH53–55." (PMID 38182755, 2024).
Ewing sarcoma (2 papers, 2012 to 2020). A small round cell tumor that lacks morphologic, immunohistochemical, and electron microscopic evidence of neuroectodermal differentiation. "Treatment of Ewing sarcoma cells with noggin eliminated phosphorylated Smad1/5." (PMID 33147457, 2020). "The GDF6 prodomain did not stimulate BMP signaling in Ewing sarcoma, whereas full-length GDF6 did (BMP signaling assessed by the levels of phosphorylated Smad1/5)." (PMID 33147457, 2020).
glomerulonephritis (2 papers, 2011 to 2016). A renal disorder characterized by damage in the glomeruli. "In this study, we addressed the role of Smad1 signalling in accelerated nephrotoxic nephritis (NTN), a model of progressive glomerulonephritis, using conditional deletion of Smad1 in Rosa26CreERT2 mice (Smad1-CKO)." (PMID 27492138, 2016). "We here confirmed that Smad1 plays a pivotal role in ECM accumulation in glomerulonephritis using Smad1-CKO mice in vivo." (PMID 27492138, 2016). "We have reported that Smad1 is a key signalling molecule that regulates the transcription of type IV collagen (Col4) in mesangial matrix expansion and is thereby involved in glomerular injury in an acute model of glomerulonephritis." (PMID 27492138, 2016). "Here we show that Smad1 plays an important role in the development of glomerular injury without affecting cell proliferation, in progressive glomerulonephritis." (PMID 27492138, 2016). "However, the mechanisms by which Smad1 is activated in glomerulonephritis have not been fully elucidated." (PMID 21445358, 2011). "However, the molecule that activates Smad1 in glomerulonephritis has not been fully elucidated." (PMID 21445358, 2011).
iron deficiency (2 papers, 2013 to 2018). "Indeed in these mice we show an increased phosphorylation of SMAD1/5/8, expected to be low in conditions of iron deficiency." (PMID 23922777, 2013).
leukemia (2 papers, 2022 to 2024). A malignant (clonal) hematologic disorder, involving hematopoietic stem cells and characterized by the presence of primitive or atypical myeloid or lymphoid cells in the bone marrow and the blood. "Our findings suggest that the loss of SMAD1 in KMT2A-rearranged leukemia with KMT2A::AFF1 promotes tumor growth." (PMID 39834944, 2024). "The opposing results of SMAD1 expression in MM6 cells demonstrate that TGF-β signaling can have diverse outcomes in KMT2A-rearranged leukemia, compatible with the versatile nature of TGF-β signaling." (PMID 39834944, 2024). "This study contributes to a deeper understanding of TGF-β signaling and the role of SMAD1, particularly concerning its potential effects on tumor growth in KMT2A-rearranged leukemia." (PMID 39834944, 2024). "To target the tumor suppressive SMAD1/S1PR2 pathway and the leukemia-supporting IRE1/XBP1s pathway, we used the S1PR2 agonist CYM-5520 and the IRE1 inhibitor B-I09, respectively." (PMID 36042317, 2022). "Further, our data showed a dampening effect of SMAD1 presence combined with TGF-β stimulation on the expression of the two KMT2A-rearranged leukemia-driving genes HOXA9 and MEIS1, which has not been described in literature yet." (PMID 39834944, 2024). "Interestingly, in the literature SMAD1 has not yet been mentioned in the context of KMT2A-rearranged leukemia." (PMID 39834944, 2024).
malignant glioma (2 papers, 2012 to 2021). A grade III or grade IV glioma arising from the central nervous system. "We examined the mRNA and protein expressions of BMP2, BMPR-II, BMPR-IA, BMPR-IB and Smad1/5/8 in normal astrocytes and malignant glioma cell lines using real-time RT-PCR and western blot analysis, respectively." (PMID 22650359, 2012).
meningioma (2 papers, 2020 to 2024). A generally slow growing tumor attached to the dura mater. "BMP4 stimulates meningioma cell proliferation and phosphorylation/activation of Smad1 playing autocrine/paracrine roles and interacting with other transforming growth factor-beta superfamily members in regulating meningioma growth and differentiation." (PMID 32244473, 2020).
metastatic tumor (2 papers, 2014 to 2022). "In addition, we found that tumor cells expressed higher levels of BMP2, N-cadherin, Vimentin and p-SMAD1/5 in the shLacZ group than in the shBMP2 group by IHC both in primary tumors (right lung) and metastatic tumors (left lung)." (PMID 36175474, 2022).
Myocardial fibrosis (2 papers, 2024 to 2025). "Gene ablation aggravated myocardial fibrosis and cardiac remodeling by suppressing SMAD1/5/8 (in vivo) (protective role)." (PMID 38745756, 2024). "MiR-486-5p also plays an important role in inhibiting myocardial fibrosis and reducing excessive deposition of extracellular matrix proteins by specifically targeting and down-regulating the expression of Smad1, a key mediator of the transforming growth factor β signaling pathway." (PMID 39944601, 2025).
myocardial ischemia (2 papers, 2021 to 2025). A disorder of cardiac function caused by insufficient blood flow to the muscle tissue of the heart. "The role of Cxcl2 and Smad1 in myocardial ischemia also have been reported." (PMID 34238326, 2021).
oral squamous cell carcinoma (2 papers, 2010 to 2021). "Downstream BMP-induced signals are mediated by inhibiting Smad1/5/9 expression in human oral squamous cell carcinoma." (PMID 34925436, 2021).
osteonecrosis (2 papers, 2021 to 2022). A none disease characterized by death of bone tissue due to a lack of blood supply. "The NONFH exosomal miR-100-5p can lead to NONFH-like damage by targeting BMPR2 and suppressing the BMPR2/SMAD1/5/9 signalling pathway, which may be involved in the pathophysiological mechanisms of nontraumatic osteonecrosis of the femoral head (NONFH)." (PMID 34256859, 2021).
peripheral nerve injury (2 papers, 2024). Injury to a peripheral nerve. "Taken together, these results suggest that the BMP10/ALK2/Smad1 axis plays a key role in pain hypersensitivity after peripheral nerve injury, which points to its stimulative ability to astrocyte." (PMID 39188955, 2024). "After peripheral nerve injury, SMAD1, -2, -4, and -5 increased, and SMAD8 decreased." (PMID 39057101, 2024).
schizophrenia (2 papers, 2017 to 2020). A major psychotic disorder characterized by abnormalities in the perception or expression of reality. "As the only target of miR-30e-5p, UBE21, does not have any reported role in schizophrenia, further studies were focused on schizophrenia-associated target genes of miR-30a-5p—i.e., BDNF, SMAD1, and NEUROD1, among which only NEUROD1 showed a significantly higher expression in patients." (PMID 32764320, 2020).
squamous cell carcinoma (2 papers, 2016 to 2017). A carcinoma arising from squamous epithelial cells. "Tumors with low LKB1 and high phospho-Smad1/5/8 expression were enriched among non-squamous cancers (adenocarcinoma) compared to squamous cell carcinomas (p = 0.012)." (PMID 26701726, 2016).
viral infection (2 papers, 2016 to 2017). "To determine the importance of upregulation of Ajuba for Smad1 to regulate cell migration, we stably introduced vector containing shRNA specifically targeting Ajuba via viral infections into Smad1 overexpression HCT116 cells." (PMID 29299158, 2017). "LSM suppressed the phosphorylation of Smad1/5/8 after control siRNA transfection, demonstrating that the cells responded to the LKB1 signals under the combined conditions of viral infection and siRNA transfection." (PMID 26701726, 2016).
acute leukemia (1 paper, 2024). A clonal (malignant) hematopoietic disorder with an acute onset, affecting the bone marrow and the peripheral blood. "The purpose of this study was to shed light on the role of TGF-β pathway components, such as SMAD1, in the disease mechanism of acute leukemias." (PMID 39834944, 2024). "In silico analysis of various hematopoietic malignancies showed that, SMAD1 expression is significantly heterogeneous in the peripheral blood and bone marrow, with particularly low levels observed in chronic lymphocytic leukemia (CLL) and acute leukemia with KMT2A rearrangements." (PMID 39834944, 2024).
adenoma (1 paper, 2017). A neoplasm arising from the epithelium. "(D) H&E, and immunohistochemistry for Ki67, β-Catenin and p-Smad1/5/8 in adenomas of WT and miR-31−/− mice resulting from AOM-DSS treatment." (PMID 28870287, 2017).
adrenocortical carcinoma (1 paper, 2020). "Notably, we next validated BMP7 and MAPK14 expression and SMAD1 activation in samples from patients with NSCLC and adrenocortical carcinoma that progressed in the lung after treatment with pembrolizumab and ipilimumab, respectively." (PMID 32973129, 2020).
aortic valve disease (1 paper, 2025). "SMAD1 expression was studied in aortic tissues from subgroups of patients with concomitant aortopathy and aortic valve disease." (PMID 40737220, 2025).
aortic valve stenosis (1 paper, 2014). Aortic valve stenosis (AVS) is a condition characterized by narrowing of the heart's aortic valve opening. "The pro-osteogenic role of BMP-2- Smad1/5/8 has been shown in human aortic valve interstitial cells from patients with calcifying aortic valve stenosis." (PMID 24586576, 2014).
arteriovenous malformations (1 paper, 2015). "On the other hand, defective Smad1 signaling in the endothelium is associated with hereditary haemorrhagic telengiectasia (HHT), which is characterized by the development of unstable, arteriovenous malformations." (PMID 25643397, 2015).
astrocytic tumor (1 paper, 2025). A glial tumor of the brain or spinal cord showing astrocytic differentiation. "Figure 2illustrates the promoter methylation status of six genes involved in the TGF-β signaling pathway—SKIL, SMAD1, SMAD3, SMAD4, BMP2, and MAPK1—across astrocytic tumors of increasing malignancy (grades G2, G3, and G4)." (PMID 40869118, 2025). "Elevated expression of SMAD1, SMAD3, and SKIL emerged as strong prognostic indicators, underscoring their potential as biomarkers and therapeutic targets in astrocytic tumors." (PMID 40869118, 2025).
astrocytomas (1 paper, 2025). "In this study, we present multi-level evidence demonstrating that key mediators of the TGF-β signaling pathway—SKIL, BMP2, SMAD1, SMAD3, SMAD4, and MAPK1—are consistently upregulated in high-grade astrocytomas." (PMID 40869118, 2025). "Compared to G2 tumors, high-grade astrocytomas (G3 and G4) exhibited elevated levels of SKIL, SMAD1, SMAD3, BMP2, and MAPK1, with most differences reaching statistical significance (p < 0.05)." (PMID 40869118, 2025).
breast tumors (1 paper, 2015). "Downregulation of SMAD1 in breast tumor cells will abrogate any BMP signaling (locally or at a distant site) in these cells." (PMID 28721365, 2015). "In addition, breast tumors revealed significant downregulation of SMAD1, which acts as a downstream mediator of the BMP signaling pathway." (PMID 28721365, 2015).
Burkitt lymphoma (1 paper, 2012). A rare form of malignant mature B-cell non-Hodgkin lymphoma. "Interrogation of SMAD1 gene expression across different NHLs showed that SMAD1 varied across different subtypes, with highest levels in Burkitt lymphoma (BL), and lowest in MCL." (PMID 23049692, 2012).
Buschke-Ollendorff syndrome (1 paper, 2024). Buschke-Ollendorff syndrome (BOS) is a benign disorder characterized by the association of osteopoikilosis lesions (``spotted bones'') in the skeleton and connective tissue nevi in the skin. "Loss of function of LEMD3 results in unique sclerosing bone disease spectrums, osteopoikilosis (MIM #166700), melorheostosis (MIM #155950) and Buschke-Ollendorff syndrome (BOS; MIM #166700).306,307 LEMD3 has been shown to antagonize BMP and TGF-β by interacting with SMAD-1, -2, -5, and -9." (PMID 38267638, 2024).
calcification (1 paper, 2020). Process by which organic tissue becomes hardened by the physiologic deposit of calcium salts. "In conclusion, our data for the first time demonstrate that celastrol attenuates high calcium–induced arterial and valvular calcification by inhibiting BMP2/Smad1/5 signalling, which may provide a novel therapeutic strategy for arterial and valvular calcification in patients with CKD." (PMID 32954678, 2020).